UPF1 (UPF1 RNA helicase and ATPase)
Diseases named in the same sentence as UPF1 in open-access papers (continued):
Sharing a sentence is not in itself a finding about the gene and the disease.
status epilepticus (1 paper, 2017). Status epilepticus is defined as a continuous seizure lasting more than 30 min, or two or more seizures without full recovery of consciousness between any of them. "We evaluated changes to NMD-associated transcripts provoked by status epilepticus by immunoprecipitating RNA from Upf1 (RIP-seq) and we tested the effects of a small molecule inhibitor of the NMD system on the occurrence of spontaneous seizures." (PMID 28128343, 2017). "Status epilepticus led to increased protein levels of Up-frameshift suppressor 1 homolog (Upf1) within the mouse hippocampus." (PMID 28128343, 2017). "Consistent with this, we detected increased Arc levels bound to Upf1 after status epilepticus in the model." (PMID 28128343, 2017). "In order to look for specific transcripts that are targeted by Upf1 we explored the data for genes that were both significantly (p < 0.05) altered after status epilepticus and had a FPKM log2 fold change ≥1.5." (PMID 28128343, 2017). "We performed RIP-seq analysis of Upf1 from control and status epilepticus samples (8 h) for both SN and cytoplasmic Upf1-bound transcripts." (PMID 28128343, 2017). "The present study included validation of RIP-seq data that confirmed status epilepticus results in increased binding of numerous mRNA transcripts to Upf1." (PMID 28128343, 2017). "Western blot analysis revealed an increase in Upf1 and p-Upf1 at 8 and 24 hours and Upf2 at 8 hours after status epilepticus in the model." (PMID 28128343, 2017). "Upf1 also co-localized with Map2, a marker of dendrites, in the hippocampus after status epilepticus, particularly around area CA2." (PMID 28128343, 2017). "The present study provides the first analysis of Upf1-bound RNA transcripts in the hippocampus of mice subject to status epilepticus." (PMID 28128343, 2017). "Western blot analysis of SN samples showed increased levels of Upf1 after status epilepticus." (PMID 28128343, 2017). "In addition to the overall increase in levels of select NMD components, we observed an increase in Upf1 levels within the synaptodendritic compartment after status epilepticus." (PMID 28128343, 2017). "We next sought to determine whether there were changes in Upf1-targeting of mRNA transcripts after status epilepticus." (PMID 28128343, 2017). "To determine whether status epilepticus drives changes in Upf1 localization we double-stained brain sections with specific antibodies against Upf1 and either the axonal marker AnkyrinB or the dendritic marker Map2." (PMID 28128343, 2017). "The present study found that status epilepticus produces changes to hippocampal levels of NMD proteins, including levels of Upf1, which is required for formation of mRNA surveillance complexes." (PMID 28128343, 2017). "To determine if status epilepticus had any effect on the expression of NMD proteins we compared levels of these proteins and phospho-Upf1, the active form, 1, 4, 8 and 24 hours after status epilepticus induced by intraamygdala KA in mice." (PMID 28128343, 2017). "Real-time PCR analysis showed the expected higher levels of Arc, FosB, Inhba, Npas4, Pchd8 and Tll1 bound to Upf1 after status epilepticus whereas levels of Slc1a2 were not different between groups." (PMID 28128343, 2017). "In contrast, Upf1 levels did not change after status epilepticus within samples from the cytoplasm." (PMID 28128343, 2017).
temporal lobe epilepsy (1 paper, 2017). A localization-related (focal) form of epilepsy characterized by recurrent seizures that arise from foci within the temporal lobe, most commonly from its mesial aspect. "Upf1 protein levels were also higher in resected hippocampus from patients with intractable temporal lobe epilepsy." (PMID 28128343, 2017).
tumor (48 papers, 2008 to 2026). "Rescue experiments were employed to reveal the underlying molecular mechanisms that mediate the tumor suppressive role of UPF1." (PMID 41293174, 2025). "Lastly, UPF1 is associated with numerous human diseases, such as various types of cancer, where it functions mostly as a tumor suppressor, but its oncogenic character has also been proved." (PMID 36766761, 2023). "The perturbation of NMD resulting from those tumor-specific mutations significantly increases the number of aberrant mRNAs that should be targeted by UPF1-mediated NMD." (PMID 36766761, 2023). "These tumor-specific mutations were shown to generate aberrantly spliced isoforms of UPF1, affecting the essential helicase domain and an important phosphorylation site." (PMID 36833284, 2023). "All in vitro results were confirmed in a xenograft model, indicating that UPF1 variant-expressing tumor tissues exhibited loss of tumorigenesis." (PMID 35453543, 2022). "The correlation regression analysis revealed that the expression of UPF1 was associated with tumor size and lymph node metastasis." (PMID 31040354, 2019). "In the present study, we demonstrated that UPF1 was significantly down-regulated in HCC tissues as compared with adjacent non-tumor tissues, and this down-regulation of UPF1 was associated with decreased survival of HCC patients." (PMID 26759305, 2016). "Further studies are now required to determine how NMD activity may change the repertoire of genes involved in MSI carcinogenesis and impact tumor progression using MMR deficient mouse models in which UPF1 activity is modified." (PMID 18612427, 2008). "Therefore, we hypothesized that UPF1-KD might affect tumor-associated macrophage activation through COX-2." (PMID 41293174, 2025). "Indeed, it was found that these tumor-specific mutations in UPF1 perturbed NMD." (PMID 36833284, 2023). "The CAPZA1[T] variant binds hnRNP K and PTBP1 to stabilize its mRNA and inhibit tumor aggressiveness, whereas the CAPZA1[G] allele promotes UPF1-mediated mRNA decay and diminishes this protective effect." (PMID 41787560, 2026). "Knockdown of brm, shg, ago, rhoGAPp190 and upf1 each significantly enhanced tumour sensitivity to trametinib plus PNU-74654 in both multigenic tumours, with the exception that shg had only weakly improved RAPp1 drug response." (PMID 41188521, 2025). "A tumor suppressive role of UPF1 was also observed in tumor cell lines, including gastric cancer, ovarian cancer and glioma cells." (PMID 41293174, 2025). "UPF1 overexpression led to a marked reduction in tumor volume compared to the control group, whereas UPF1 knockdown significantly enhanced tumor growth in vivo." (PMID 41293174, 2025). "UPF1 expression in subcutaneous tumor tissues was verified using multiplex immunohistochemistry (mIHC)." (PMID 41293174, 2025). "Direct NMD inhibition using small-molecule inhibitors (e.g., NMDI-1, CC-115) or genetic suppression of NMD factors (e.g., UPF1 knockdown) can restore the expression of TSGs or enhance tumor antigenicity." (PMID 41219960, 2025). "Previous studies have revealed that SNAI3-AS1 is upregulated in HCC, and can promote tumor cell proliferation and metastasis by activating UPF1/Smad7 signaling pathway and by acting as a sponge for miR-27-3p and miR-34a-5p to upregulate PEG10." (PMID 37202791, 2023). "LncRNA and microRNA can interact with UPF1, resulting in its tumor-suppressive functions in various cancers." (PMID 36766761, 2023). "IHC also confirmed that UPF1 expression was downregulated and negatively correlated with tumor stage." (PMID 35986402, 2022).
tumor (continued). "IVIS assays in an orthotopic xenograft model showed that tumors in mice injected with sh-SLERCC#3 cells had stronger luminescence intensity, higher tumor weights, higher Ki67 scores and lower UPF1 scores relative to mice injected with sh-NC cells." (PMID 35986402, 2022). "UPF1 can act as a tumor suppressor to induce apoptosis of tumor cells, inhibit cell proliferation and weaken the cell stemness of tumor." (PMID 36421841, 2022). "On the other hand, as a master regulator of nonsense-mediated mRNA decay (NMD), Up-frameshift protein 1 (UPF1) is a tumor regulator and a potential biomarker." (PMID 35831298, 2022). "In tumorigenesis, recent investigations have demonstrated the inhibitory role of UPF1 in tumor progression in multiple cancers." (PMID 35831298, 2022). "Taken together, we concluded that RBM47 functioned as a tumor suppressor by upregulating UPF1, acting as a DNA/RNA binding protein at the transcriptional and posttranscriptional levels." (PMID 35831298, 2022). "The UPF1 overexpression-mediated increase of DUSP1 activated tumor suppressor signaling, ultimately inhibiting cell growth." (PMID 35453543, 2022). "Our study found that UPF1 expression levels were significantly lower in ccRCC tissues when compared with adjacent non-tumor tissues." (PMID 36421841, 2022). "IHC in paraffin-embedded tumor samples from 10 ccRCC patients also showed that UPF1 protein staining was relatively weaker in the tumor cells compared with that in the adjacent non-tumor kidney tissues." (PMID 36421841, 2022). "Briefly, UPF1-mediated tumorigenicity in EC was primarily attributed to the self-renewal capacity of ECSCs, and silencing of UPF1 exerted tumor-suppressive effects on ECSCs." (PMID 35318304, 2022). "Taking into consideration of the enrichment of GO and KEGG, the Upframeshift 1 (UPF1), which is a tumor suppressor in HCC, was predicted to be a direct target of RBM47." (PMID 35831298, 2022). "Specifically, 5 × 103 ECSCs transfected with sh-UPF1 were required to form a xenograft tumor, while only 100 ECSCs transfected with sh-NC were enough." (PMID 35318304, 2022). "The limiting dilution assay implied that UPF1 knockdown hindered the tumor initiation capacity of ECSCs." (PMID 35318304, 2022). "Our data robustly demonstrated that UPF1 knockdown hindered the malignant behaviors of ECCs and inhibited tumor growth in vivo." (PMID 35318304, 2022). "Subcutaneous xenograft model also showed that knockdown of SLERCC significantly promoted tumor volume, weight and Ki67 expression in xenografts as well as suppressed UPF1 expression." (PMID 35986402, 2022). "We know that UPF1 behaves as a tumor suppressor in multiple ways through targeting different tumor-associated proteins." (PMID 35831298, 2022). "(C) Line graph comparing tumor volume between mice injected with control (AdCas9; Cas9 only) or treatment (AdUpf1; Cas9 with Upf1-targeting guide RNAs) KPC cells." (PMID 33404013, 2021). "UPF1 expression was higher in 28 (28/42, 66.67%) tumor samples than that in adjacent normal samples." (PMID 34520393, 2021). "It is revealed that UPF1 is downregulated in hepatocellular carcinoma and inhibits the tumor progression." (PMID 34021129, 2021). "In these patients, UPF1-positive was detected in 52 (68.4 %) of the tumor tissues, whereas only 4 (5.3 %) of the normal tissues were UPF1-positive (P < 0.001)." (PMID 34021129, 2021). "The tumor volume and weight in mice with UPF1 overexpression was significantly higher than that in the control group." (PMID 34520393, 2021). "In line with these clinical findings, there is experimental data showing that overexpression of UPF1 reduces the number and size of cultured tumor cell colonies when compared to control cells of several cancer cell lines." (PMID 33926465, 2021). "Previous studies have demonstrated that UPF1 was a key regulator of mRNA decay for certain tumor‐suppressive genes." (PMID 31919993, 2020).
tumor (continued). "Our previous studies showed that promoter methylation caused Upf1 downregulation in HCC and that Upf1 regulated hepatocarcinogenesis and acted as a tumor suppressor gene in HCC." (PMID 32802196, 2020). "Our previous study indicated that Upf1 is a potential tumor suppressor gene that regulates hepatocarcinogenesis by targeting Smad7." (PMID 32802196, 2020). "Our previous research showed that Upf1, as a tumor suppressor gene, plays an important role in hepatocarcinogenesis." (PMID 32802196, 2020). "IHC illustrated that the expression of UPF1 was decreased in HCC tissues compared with adjacent non-tumor tissues." (PMID 31040354, 2019). "Mechanistically, CSL binds and anchors Ku70/Ku80 and UPF1 to telomeric DNA, orchestrating crucial aspects of telomere biology with relevant implications for tumor development." (PMID 31467287, 2019). "Recently, other potent small molecule inhibitors selective for SMG1 kinase have been identified to inhibit UPF1 phosphorylation in cells and in mouse tumor xenograft models, where they promote anti-tumor efficacy (JMB, unpublished)." (PMID 28533900, 2017). "A great downregulation of UPF1 due to promoter hypermethylation was observed in tumor tissues compared to their adjacent normal tissues." (PMID 26759305, 2016). "In this study, we found UPF1 is a potential tumor suppressor, which negatively regulates proliferation of cancer cells, we also observed that UPF1 is down-regulated in HCC tissues." (PMID 26759305, 2016). "The results of our study suggest that decreased UPF1 expression in NPC cells might enhance tumor progression." (PMID 41293174, 2025). "In HCC, UPF1 was demonstrated to act as a tumor suppressor via multiple pathways." (PMID 35831298, 2022). "Mechanistically, SLERCC could directly bind to UPF1 and exert tumor-suppressive effects through the Wnt/β-catenin signaling pathway, thereby inhibiting progression and metastasis in RCC." (PMID 35986402, 2022). "However, there is evidence that UPF1 acts as a tumor suppressor in HCC, and RBM47 reveals clinical value in some other cancers." (PMID 35831298, 2022). "Next, seven independent proven algorithms were utilized to evaluate the immunocyte proportion in each sample to comprehend the landscape of immunocyte infiltration status of the ccRCC tumor microenvironment, and T cells and macrophages were identified as significantly correlated with UPF1." (PMID 36421841, 2022). "Recently, several studies have pointed out that UPF1 is a potential tumor suppressor in HCC." (PMID 35453543, 2022). "Recently, UPF1 has been found to be closely related to the tumor immune microenvironment." (PMID 36421841, 2022). "Additionally, a close relationship between UPF1 expression level and tumor immune microenvironment was explored by analyzing the GSE data of ccRCC single cell sequencing (scRNA)." (PMID 36421841, 2022). "Inhibition of UPF1 may be used to lower the chances of CSCs being the tumor origin and may be beneficial for chemoprevention while sparing normal endometrial stem cells via the LINC00963/miR-508-5p/SOX2 pathway." (PMID 35318304, 2022). "In this study, we highlighted the function of UPF1 as a tumor suppressor in HCC growth." (PMID 35453543, 2022). "UPF1 acts, in part, by destabilizing the NMD substrate encoding the TGFβ inhibitor, Smad7, and stimulating TGF signaling, and several studies have shown that UPF1 exerts suppressive roles in tumor progression." (PMID 35338348, 2022). "UPF1 may play a tumor suppressive role in ccRCC and is involved in the regulation of the immune microenvironment." (PMID 36421841, 2022). "In current study, we determined that RBM47 could exert tumor suppressive effects via UPF1 and we identified several DNA/RNA binding motifs by sequencing." (PMID 35831298, 2022). "Similarly, the tumor volume and weight in mice with UPF1-inhibited cells significantly lower than that in the control and wild-type groups." (PMID 34520393, 2021).
tumor (continued). "Our results showed that UPF1 expression in tumor tissues was higher than that in normal tissues." (PMID 34520393, 2021). "Second, as our assays were performed in the complex setting of in vivo tumorigenesis, we cannot infer how inducing the reported Upf1 exon skipping might affect tumor cell proliferation in the controlled setting of in vitro growth." (PMID 33404013, 2021). "Functional investigations showed that SNAI3-AS1 may affect tumorigenesis by inducing tumor epithelial to mesenchymal transition via regulating the UPF1/Smad7 signaling pathway." (PMID 32802843, 2020). "Our previous research confirmed the tumor-suppressive effect of Up-frameshift 1 (Upf1) in HCC." (PMID 32802196, 2020). "Our results were consistent with these previous reports that UPF1 was a tumor suppressor." (PMID 31040354, 2019). "Furthermore, it was reported UPF1 acts a tumor suppressive gene in HCC, but, the role played by UPF3A, in the pathogenesis of HCC, has not been well studied." (PMID 31856847, 2019). "In addition, the rescue experiments were conducted to prove that SNAI3‐AS1 promotes tumour EMT by regulating UPF1." (PMID 31264769, 2019). "Using the large annotated multi-tumor cancer genome sequencing resource, we identified 41 mutations (31 residues in the CH-domain and 10 residues at the ATP-binding site) across the coding region of the core component of the NMD pathway, UPF1." (PMID 31718065, 2019). "UPF1 was downregulated in HCC tissues compared with adjacent non-tumor tissues." (PMID 26759305, 2016). "Our findings revealed that UPF1 is a potential tumor suppressive gene and may be a potential therapeutic target for HCC." (PMID 26759305, 2016). "We found UPF1 overexpressed dramatically inhibited tumor growth." (PMID 26759305, 2016). "Our findings suggest that reduced expression of UPF1 in NPC might contribute to tumor progression." (PMID 41293174, 2025). "The ATP-dependent RNA helicase Nam7/Upf1, which functions in nonsense-mediated mRNA decay but is also required for telomere length maintenance, was also significantly upregulated (P < 0.05); its human homolog UPF1 also helps preserve telomere stability and is a potential tumor suppressor." (PMID 37638880, 2023). "Furthermore, mechanistically, SLERCC could directly bind to UPF1 and exert tumor-suppressive effects through the Wnt/β-catenin signaling pathway, thereby inhibiting the progression and metastasis of RCC." (PMID 35986402, 2022). "Therefore, although we determined that RBM47 could exert tumor suppressive effects via UPF1, it may have additional targets in HCC." (PMID 35831298, 2022). "Altogether, it seems that typically NMD works as a tumor suppressor pathway by regulating the expression of genes involved in cell proliferation, differentiation and survival, and that tumors with impaired NMD, like the ones with mutated UPF1, have favorable conditions for tumor proliferation." (PMID 33926465, 2021). "Considering that the potential UPF1 targets were enriched mainly in immune-related signaling pathways, we focused on COX-2 and PD-L1, two crucial factors in immunomodulation and tumor progression, as candidate UPF1 targets in NPC." (PMID 41293174, 2025). "Therefore, we may speculate that RBM47 could inhibit HCC tumor cell processes by increasing UPF1." (PMID 35831298, 2022). "Tumor volume, weight, tumor growth rate, and tumor take rate (TTR) were lower for the sh-UPF1 group than the sh-NC group." (PMID 35318304, 2022). "To recapitulate the effect of NMD activity in the outcome of tumor progression, we generated different tumor cell lines with their NMD machinery compromised by blocking key NMD factors -SMG1, UPF1, UPF2- via CRISPR." (PMID 36443756, 2022). "To investigate UPF1 expression in EEC, we examined the expression of UPF1 in EEC cases and tumor cell lines." (PMID 34520393, 2021). "As direct targets of PVT1, UPF1 and miR-128-3p mediate the roles of PVT1 in tumor proliferation and metastasis." (PMID 34922601, 2021).